ATM (ATM serine/threonine kinase)
Diseases named in the same sentence as ATM in open-access papers (continued):
Sharing a sentence is not in itself a finding about the gene and the disease.
prostate carcinoma (continued). "In a recent case series of patients with prostate cancer, a high proportion of ATM gene variants were present in plasma attributable to CHIP, impacting the ability to identify patients eligible for PARP inhibitors and the association with clinical efficacy." (PMID 34771462, 2021). "Resveratrol switched radioresistant prostate cancer cells back to sensitive phenotype by inhibiting ATM phosphorylation and its target protein H2AX, causing cell cycle arrest and subsequently cell death." (PMID 33330091, 2020). "Taken together, these findings provide pre-clinical data for future clinical evaluation of ATM inhibitors as a neoadjuvant/adjuvant in combination with radiation therapy in prostate cancer patients harbouring PTEN mutations." (PMID 33396656, 2020). "Our findings provide a strong rationale for evaluating loss of PTEN in prostate cancer as a therapeutic target for ATM inhibitor in combination with radiotherapy in the clinical setting." (PMID 33396656, 2020). "Pre-treatment of prostate cancer cells with zerumbone significantly decreased the radiation-induced expression of phosphorylated ATM (ataxia telangiectasia-mutated) and suppressed the expression of JAK2 and STAT3, which are involved in DNA damage repair." (PMID 30781671, 2019). "One ATM-mutated prostate cancer had a significantly higher frequency of extratumoral CD45 positive lymphocytes." (PMID 31549213, 2019). "Defects in DNA damage repair caused by mutations in BRCA1/2, ATM or other genes have been shown to play an important role in the development and progression of prostate cancer." (PMID 31549213, 2019). "Taken together, we have shown that Andrographolide is an effective anti-cancer compound for prostate cancer by regulating genes associated to double-strand breaks such as ATM, NBN, BRCA2 BLM, PALB2 and BLM." (PMID 30800220, 2019). "We also found that DT treatment induced the cell cycle of prostate cancer cells entering S phase and increased the protein expression of DNA damage response proteins (rH2AX and phosphorylated ataxia telangiectasia-mutated [ATM]) in DU145 cells and PC-3 cells." (PMID 29386061, 2018). "ATM is one of only 22 genes recurrently mutated in 3 or more cancers (renal cell, lung adenocarcinoma, and prostate cancer)." (PMID 28055970, 2017). "Here we show that AtmKD also compromises HR, a pathway implicated in breast, ovarian, pancreatic and prostate cancers, in which recurrent ATM missense mutations were recently identified." (PMID 27304073, 2016). "SNPs rs11615 (ERCC1) and rs17503908 (ATM) appeared as risk factors for prostate cancer aggressiveness." (PMID 25540025, 2014). "ATM/ATR inactivation is a crucial step in promoting androgen-induced genomic instability and prostate carcinogenesis, and some missense variants of the ATM gene have been shown to confer a moderate increased risk of prostate cancer." (PMID 25540025, 2014). "In another study, the same ATM variant was also reported to cause a twofold increase in the risk of developing prostate cancer." (PMID 23272087, 2012). "We have investigated the possible association between five ATM sequence variants and an increased risk of prostate cancer." (PMID 15280931, 2004). "Consistent with BRCA2 and ATM showing association with disease severity, their effect sizes were larger in this aggressive prostate cancer versus controls analysis compared to the overall prostate cancer versus controls analysis." (PMID 39971927, 2025). "ATM Mutation: The ATM mutation is associated with a fourfold increased risk of prostate cancer." (PMID 41541272, 2025). "Furthermore, it is worth noting that ATM mutations have shown variable sensitivity to PARP inhibitors in preclinical studies using prostate cancer models." (PMID 40622001, 2025). "However, in other studies, ATM loss was notably higher in high-grade prostate cancer with a GS of 9 or higher." (PMID 40660132, 2025).
prostate carcinoma (continued). "Similarly, studies on prostate cancer have reported a higher frequency of ATM gene mutations in white and black populations compared to Asians." (PMID 39541191, 2024). "Still other data suggest that specific ATM single nucleotide polymorphisms (SNPs), such as rs1801516 (c.5557G>A, pAsp1853Asn), are associated with radiation toxicity in breast and prostate cancer patients; however, meta-analyses examining this question have also been conflicting." (PMID 37206490, 2023). "Finally, germline PVs in BRCA1, BRCA2, PALB2 or ATM were independently associated with short time to castration in patients with advanced prostate cancer." (PMID 37511593, 2023). "Recent studies have implied that patients with ATM-mutant prostate cancer may have a higher risk of prostate cancer progression and reduced survival compared to those without ATM mutations." (PMID 37345203, 2023). "In our cohort, the ATM 3161 G > C variant was associated with an increased prostate cancer risk." (PMID 35740343, 2022). "A differential response to olaparib treatment among men with metastatic castration-resistant prostate cancer harboring BRCA1/2 versus ATM mutations has been observed, in which patients with BRCA1/2 mutations respond to olaparib treatment but not those with ATM mutations." (PMID 36429046, 2022). "In a study of 4607 ATM pathogenic variant carriers and 623,135 controls, variant carriers reported a personal history of ductal invasive breast cancer (33.4%), prostate cancer (32.8%), ovarian cancer (4.4%), colorectal cancer (2.9%), and pancreatic cancer (1.4%)." (PMID 35163129, 2022). "Somatic ATM loss rate can also happen in sporadic pancreatic cancer and prostate cancer." (PMID 35563100, 2022). "Our data with RAD51B are consistent with published literature and our results with ATM are in agreement with the differential responses observed in patients with prostate cancer harboring tumors with mutations in ATM treated with olaparib when compared with those carrying BRCA2 mutations." (PMID 36969741, 2022). "Importantly, ATM mutations were detected in prostate cancer index cases from two families in which close relatives with breast/ovarian cancer had previously undergone limited ATM screening for the 7271 variant." (PMID 35892882, 2022). "Some researchers found a four-fold increased risk for pancreatic cancer, a three-fold increase for stomach cancer, and a two- to three-fold increase for prostate cancer and confirmed the previously known two-fold invasive ductal BC in patients with an ATM mutation." (PMID 34068084, 2021). "Poly (ADP-ribose) polymerase (PARP) inhibitors, for example, are used for BRCA1/2-positive breast, ovarian, and pancreatic cancer and have been FDA approved in the United States for castration-resistant ATM-deficient prostate cancer following a recent clinical trial." (PMID 34262154, 2021). "ATM is frequently mutated in prostate cancer, as well as somatic and hereditary forms of pancreatic cancers, suggesting that patients with these cancers might also benefit from treatment with a PARP inhibitor." (PMID 32183301, 2020). "In addition, we characterized the immune infiltrate in seven prostate cancer biopsies that were either BRCA2 or ATM mutated or wild type." (PMID 31549213, 2019). "Also other studies have showed similar results finding approximately 12% and 8% of prostate cancer patients carrying a BRCA2 or ATM mutation, respectively." (PMID 31357527, 2019). "In addition, we analyzed seven prostate cancer biopsies that were either BRCA2 or ATM-mutated in comparison with wild-type tumors." (PMID 31549213, 2019). "TOPARP-A (The Trial of PARP Inhibition in Prostate Cancer) phase 2 trial studied the PARP inhibitor olaparib in mCRPC patients showing good response rates particularly for BRCA1/2 or ATM gene-mutated tumours that justified the breakthrough therapy designation by FDA (Food and Drug Administration)." (PMID 29606109, 2018).
prostate carcinoma (continued). "Furthermore, some missense variants of the ATM gene have been shown to confer a moderate increased risk of prostate cancer." (PMID 23272087, 2012). "Indeed, some missense variants of ATM gene mutation have previously been shown to confer increased risk of prostate cancer." (PMID 23272087, 2012). "To evaluate the hypothesis that variants in ATM itself might be associated with prostate cancer risk, we genotyped five ATM variants in DNA from 637 prostate cancer patients and 445 controls with no family history of cancer." (PMID 15280931, 2004). "PVs in the ATM gene have been reported to have an increased predisposition to develop a wide range of cancers including breast, ovarian, pancreatic, colorectal, uterine, gastric, and/or prostate cancers as well as colorectal polyps consistent with our own findings." (PMID 34326862, 2021). "Thus, our findings may help to understand the association between ATM mutation and prostate cancer development." (PMID 23272087, 2012). "Thus, we hypothesised that the ATM gene, whose protein functions upstream of these known susceptibility genes, could also be a mutation target in prostate cancer." (PMID 15280931, 2004). "In order to assess whether ATM variants play a pathogenic role in prostate cancer development, we compared the frequencies of five ATM single-nucleotide polymorphisms (SNPs) 5557G>A, 5558A>T, 3161C>G, ivs38-8t>c, ivs38-15g>c in 618 British prostate cancer cases and 445 controls." (PMID 15280931, 2004). "Of the gene-disease associations not reported previously, associations reaching exome-wide associations using all methods included MSH6 for endometrial cancer, ATM for prostate cancer, and MED9 (MIM: 609878) for melanoma." (PMID 40073867, 2025). "Saruparib is a first-in-class PARP1 inhibitor with exquisite PARP1 selectivity that is being tested in the phase 1/2a PETRA trial in pretreated solid tumors, including prostate cancer, with a BRCA, RAD51, or ATM mutation." (PMID 39882554, 2025). "Recent studies have also demonstrated that a substantial proportion of pancreatic and prostate cancer patients harbor mutations in key HRR genes, notably BRCA1/2, ATM, PALB2, and CDK12." (PMID 40830526, 2025). "Here, we validate BRCA2, ATM and CHEK2 deleterious rare variants as significant risk factors, and reproduce the recently described association of SAMHD127 with prostate cancer in UKB and replicate the finding in additional cohorts." (PMID 39971927, 2025). "In BRCA1/2-mutant HGSOC and BRCA2/ATM-mutant prostate cancer, M2 macrophages exhibit a preferential accumulation within regions of proliferating tumor cells." (PMID 40830526, 2025). "In prostate cancer cells, quercetin reduces the expression of key DNA repair proteins, including ATM and PARP1, and enhances radiosensitivity by blocking ATM activation." (PMID 40725041, 2025). "An ATM gene deletion of exons 27 to 28 was detected in four unrelated patients affected with colorectal, ovarian, and prostate cancers." (PMID 40065011, 2025). "Germline BRCA2 pathogenic variants (PVs) are known to cause ~4% of prostate cancer, but other homologous repair genes, BRCA1, ATM, PALB2 and Lynch syndrome genes are also involved." (PMID 40046829, 2025). "Genes associated with prostate cancer at exome‐wide significance include BRCA2, a known risk factor, as well as other breast‐cancer risk genes CHEK2 and ATM for which previous evidence has been more equivocal." (PMID 39749474, 2025). "A study by The Prostate Cancer Transatlantic Consortium (CaPTC) utilizing whole exome sequencing to determine genetic variants in Nigerian patients with advanced prostate cancer identified high frequencies of mutations in the BRCA1, BRCA2, APC, and ATM genes." (PMID 40313245, 2025). "Where AR upregulation is found in prostate cancer, the ATM (ataxia telangiectasia mutated) gene’s downregulation, or complete loss, is found." (PMID 40699691, 2025).
prostate carcinoma (continued). "In accordance with previously published data showing that alpha particles activate ATM,13–15 Ra-223 increased ATM signaling in prostate cancer bone metastases." (PMID 40978127, 2025). "Pathogenic mutations in cancer-driven genes like ATM, CHEK2, PALB2, and XRCC2 have been reported to increase the risk of different malignancies, especially breast and prostate cancers." (PMID 38784039, 2024). "to evaluate the association between ATM, TP 53 and MDM 2 polymorphisms in patients with prostate cancer and morbidity after radiotherapy." (PMID 39132508, 2024). "For prostate cancer, the cumulative risks by age 80 were 31% (23% to 38%) for ATM PTV carriers and 25% (20% to 29%) for CHEK2 PTV carriers." (PMID 39209703, 2024). "An improved understanding of individual risk would account for ethnicity, advancing age, family history of prostate cancer, and genetics (eg, mutations in BRCA1, BRCA2, ATM, and the mismatch repair genes)." (PMID 38583453, 2024). "Mechanistically, MYCN promoted miR‐421 upregulation, consequently enhanced ATM expression and its phosphorylation, and then alleviated the senescence of castration‐resistant C4‐2 prostate cancer cell." (PMID 39372390, 2024). "Our data confirmed that shRNA mediated stable knockdown of well-known HR genes BRCA2/ATM in a prostate cancer cell line model led to 8- to 12-fold increased sensitivity toward LP-184, as compared with only 2- to 8-fold increased sensitivity toward olaparib." (PMID 38630886, 2024). "Further, in a phase 2 trial of olaparib in patients with advanced, castration-resistant prostate cancer, responses were observed in 4 patients with ATM aberrations." (PMID 39085400, 2024). "For example, the fungal metabolite galiellalactone induces cell cycle arrest and apoptosis in prostate cancer cells via ATM phosphorylation." (PMID 37208425, 2023). "P/LP/D status aggregated across BRCA2, ATM, NBN, and PALB2 was strongly associated with risk of overall prostate cancer (OR = 4.51; 95% CI = 2.18–9.33; P = 4.75 × 10−05) and metastatic disease (OR = 6.92; 95% CI = 2.34–20.49; P = 4.76 × 10−04)." (PMID 38014910, 2023). "In the current study, the set of genes (ATM, BRCA2, PALB2, and NBN) were those previously shown to be strongly associated with prostate cancer risk in this African ancestry sample." (PMID 38014910, 2023). "gDNA segregation analysis confirmed a further six prostate-cancer-affected relatives as carriers; a final cohort for analysis contained fifteen patients (ATM n = 9, CHEK2 n = 2 and HOXB13G84E n = 4)." (PMID 35892882, 2022). "ATM and CHEK2-associated cancers were D’Amico intermediate or high risk, comparable to our previously published BRCA2 and BRCAX prostate cancer cohort." (PMID 35892882, 2022). "We provide evidence that novel germline mutations in ATM and CHEK2 are associated with aggressive prostate cancer." (PMID 35892882, 2022). "BRCA2 variants were the most prevalent at 5.3%, and variants in ATM, CHEK2, PALB2, BRCA1, and RAD51D were also more common among men with lethal prostate cancer." (PMID 36446039, 2022). "The frequencies of mutations in ATM and BRCA1 and BRCA2 were compared in 313 men who died of prostate cancer and 486 men with localized prostate cancer." (PMID 35732815, 2022).
prostate carcinoma (continued). "TOPARP-A assessed anti-tumour activity of olaparib in a sporadic metastatic castration-resistant prostate cancer population, whilst TOPARP-B was conducted in a subset with known genomic background, specifically BRCA2 or ATM mutations." (PMID 36010882, 2022). "The recent emergence of potent ATR inhibitors has renewed interest in determining the ATM gene or ATM protein status in prostate cancer and other malignancies." (PMID 35008949, 2022). "Whole-exome and transcriptome profiling of 150 metastatic castration-resistant prostate cancer found that more than 19% of them have at least one mutation in BRCA1, BRCA2, ATM and CDK12." (PMID 36371386, 2022). "In support of those earlier observations, we discovered in prostate cancer cells that different pools of ATM protein were being activated at different time points." (PMID 36408163, 2022). "GJB2, MET, MUTYH and VHL mutations ranked top in kidney cancers, and ATM and CHEK2 mutations ranked top for bladder cancer, while ATM and BRCA1 mutations ranked top for prostate cancer." (PMID 36451132, 2022). "As previously discussed, individuals with a germline mutation in several genes (BRCA2, ATM, PALB2) are at increased risk for biochemical recurrence and prostate cancer-specific mortality." (PMID 35732815, 2022). "Among 743 Black prostate cancer patients, we identified 26 unique pathogenic (P) or likely pathogenic (LP) variants in 14 genes (including HOXB13, BRCA1/2, BRIP1, ATM, CHEK2, and PALB2) among 30 men, or approximately 4.0% of the patient population." (PMID 36446039, 2022). "Other genes implicated in the development of prostate cancer include those involved in Homologous Recombination DNA repair: BRCA1 in 199452, CHEK2 in 200353,54, ATM in 200455, and PALB2 in 200856." (PMID 35732815, 2022). "A meta-analysis showed a significant association between the ataxia telangiectasia mutated (ATM) rs1801516*Asn allele with increased risk of radiation-induced tissue toxicity in breast and prostate cancers." (PMID 34838041, 2021). "In this case series study of 69 men with advanced prostate cancer, 7 (10%) had CHIP variants in genes used for US Food and Drug Administration-approved indications of PARPi treatment, most frequently in ATM." (PMID 33151258, 2021). "The most common mutations involved in prostate cancer include BRCA1/2; ATM (odds ratio (OR) = 2.18), HoxB13 (OR = 3.23), genes involved in repairing mismatched genes and genes associated with Lynch Syndrome (OR = 4.87), and CHEK2 (OR = 1.98)." (PMID 33937056, 2021). "In prostate cancer cells, quercetin significantly reduced the expression of ATM, PARP1, and DNA-PKcs." (PMID 33330091, 2020). "Further studies, as well as the study of rational drug combinations, are now needed to elucidate how to best evaluate and treat metastatic castration-resistant prostate cancer with ATM alterations." (PMID 31806540, 2020). "The prime example is using poly (ADP-ribose) polymerase (PARP) inhibitors for the treatment of adults with advanced breast, ovarian, and prostate cancers in the context of germline mutations in DDR genes, such as BRCA1, BRCA2, ATM, or PALB235–37." (PMID 32371905, 2020). "Genome sequencing has revealed that ATM is mutated in a variety of human cancers, including mantle cell lymphoma (MCL), colorectal, lung and prostate cancers." (PMID 32183301, 2020).